H2AX (H2A.X variant histone)
Diseases named in the same sentence as H2AX in open-access papers (continued):
Sharing a sentence is not in itself a finding about the gene and the disease.
hepatocellular carcinoma (25 papers, 2012 to 2025). A malignant tumor that arises from hepatocytes. "In a model of poorly differentiated hepatocellular carcinoma cells, the cell cycle arrest was possibly caused by histone H2AX phosphorylation, resulting from DNA damage." (PMID 32197515, 2020). "Our present study demonstrates that caffeine treatment diminished γ-H2AX levels in hepatoma cells and increased cell survival under UV-induced DNA damage, consistent with DDR attenuation." (PMID 41292688, 2025). "In patients with hepatocellular carcinoma, increased γ-H2AX positivity has also been observed in liver biopsies, indicating significant injury." (PMID 41515946, 2025). "A 3 h pre-treatment with 1 mM HDACi Valproic acid (VPA) and mid-SOBP protons prolonged appearance of γ-H2AX foci in Hep3B and Huh7 hepatocellular carcinoma cell lines." (PMID 39598379, 2024). "Multifactorial Cox regression of 11 prognostic genes resulted in seven independent risk genes affecting the prognosis of patients with hepatocellular carcinoma, namely ENO1, NDRG1, NPM1, H2AX, IL33, MT3 and TXNRD1." (PMID 38097352, 2023). "In line with this notion, we found that the levels γ-H2AX, as an indicator of DNA DSBs, were markedly escalated in hepatomas formed in DEN-treated mice, and this was attenuated by SFN administration." (PMID 35628208, 2022). "Our findings are also in line with earlier work by Li and co-authors, who showed that even short term pre-culturing of hepatocellular carcinoma cell lines with Sorafenib resulted in significantly fewer cells with γ-H2AX foci after subsequent irradiation." (PMID 29435166, 2018). "To evaluate the clinical usefulness of γ-H2AX in hepatocellular carcinoma (HCC), we measured the level of γ-H2AX in HCC, dysplastic nodule, and nontumorous liver diseases." (PMID 23533353, 2013). "DNA damage had been almost completely repaired in the irradiated hepatocellular carcinoma cells since less than 5% of the irradiated cells contained significant DNA damage (≥ 10 γ-H2AX foci)." (PMID 23088517, 2012). "Metformin combined with IR was recently reported to induce cytotoxicity of hepatoma cells more than IR alone did, by inhibiting DNA repair, which was mediated by the accumulation of cells in the cell cycle G2/M phase and disappearance of γ-H2AX expression." (PMID 26599019, 2015). "To assess whether the schedule-dependent effect of sorafenib on irradiated cells is associated with mitotic catastrophe, we monitored DNA damage in irradiated hepatocellular carcinoma cells by examining γ-H2AX foci with immunofluorescence microscopy." (PMID 23088517, 2012). "RNA-seq data have showed that the overexpression of γ-H2AX in 19 types of cancers and γ-H2AX was positively correlated with the poor survival rate of hepatocellular carcinoma (HCC) patients, indicating the pivotal role of γ-H2AX in HCC." (PMID 41292688, 2025). "Pre-treatment with 5 nM Panobinostat increased the γ-H2AX foci yield at 24 h post irradiation with 6 Gy mid-SOBP protons in Huh7 and Hep3B hepatocellular carcinoma cell lines." (PMID 39598379, 2024). "Consistent with our previous findings, USP21 knockdown in hepatoma cell lines resulted in reduced BRCA2 expression and a concomitant increase in DNA damage, as measured by H2AX phosphorylation." (PMID 28743957, 2017). "On the other hand, DNA double strand breaks, evaluated by the formation of γ-H2AX foci, a marker correlated with micronuclei formation, were induced by BPA but not by BPS in human hepatocellular carcinoma cells." (PMID 33776939, 2021).
pancreatic cancer (23 papers, 2013 to 2025). "In our current study, we further demonstrated that SMAD4 deficiency promotes DSB repair in pancreatic cancer caused by ionizing radiation, as evidenced by more quickly decreased expression of γ-H2AX levels." (PMID 39528473, 2024). "Correlation analysis between SORBS1 and H2AX revealed a correlation coefficient of –0.302 in pancreatic cancer (n = 179)." (PMID 40918460, 2025). "The results of WB indicated that in the radioresistant pancreatic cancer cells, the cyclin D1, Bax, CDk4, cleaved caspase-3, Bcl-2, and γ-H2AX proteins were upregulated to varying degrees." (PMID 36276285, 2022). "With this aim, the expression level of phosphorylated H2A histone family member X (γH2AX) and the number of γH2AX-positive foci were evaluated in pancreatic cancer cells treated by HDACi alone or combination with AZD2461." (PMID 35216385, 2022). "The Gem@TpHResMic displayed relevant cellular internalization and greater antitumor properties than free Gem in 2D and 3D models of pancreatic cancer, by generating massive damage to DNA, in terms of H2AX phosphorylation and apoptosis induction." (PMID 35008170, 2021). "Western blot of phosphorylated H2AX (γH2AX), a reflection of DNA double-strand breaks (DSBs), showed a considerably up-regulation of the protein in pancreatic cancer cells treated with anlotinib." (PMID 33748143, 2021). "AZD7762, a Chk1 inhibitor prevents the formation of Rad51 foci in pancreatic carcinoma cells and also leads to persistent γ-H2AX in response to γ-radiation." (PMID 25909291, 2015). "We therefore asked whether the cytotoxic effect mediated by c-Myc inhibition could correlate with increased DNA damage and found that the phosphorylation of H2AX (γH2AX), indicating the occurrence of such effect, increased in both pancreatic cancer cell lines." (PMID 36289751, 2022). "Likewise, gemcitabine alone produces an increase in γ-H2AX foci in in vitro models of pancreatic cancer." (PMID 36614121, 2022). "In contrast, a sustained induction of γ-H2AX may have an opposing effect to increase FL118 effects on pancreatic cancer cell killing." (PMID 30285798, 2018). "To assess this, we examined the formation of γ-H2AX foci in response to olaparib in various cell groups, including control cells, NLRP4-knockdown cells, NLRP4-overexpressing pancreatic cancer cells, and MitoQ-treated cells." (PMID 39187531, 2024). "Intriguingly, an investigation was conducted on the γ-H2AX foci under various cellular conditions, including control, NLRP4 knockdown, NLRP4 overexpression in pancreatic cancer cells, and MitoQ treatment, after olaparib treatment." (PMID 39187531, 2024). "P19-gemcitabine and P19–5-FU phosphorylated histone H2AX for Ser139 (ɤ-H2AX) that is a biomarker of DNA double strand breaks (DSBs) and inhibited cell proliferation in PANC-1, gemcitabine-resistant pancreatic cancer cells." (PMID 34823601, 2021). "This is similar to what was observed in pancreatic cancer cell lines where gemcitabine, when combined with AZD1775 increased the amount of γ-H2AX staining by flow cytometry." (PMID 32204315, 2020).
leukemia (19 papers, 2010 to 2025). A malignant (clonal) hematologic disorder, involving hematopoietic stem cells and characterized by the presence of primitive or atypical myeloid or lymphoid cells in the bone marrow and the blood. "Another sponge terpenoid, 10-acetylirciformonin B, produced double-strand breaks detected both by the neutral comet assay and histone γ-H2AX expression in human leukaemia (HL 60) cells; the DNA breakage was followed by apoptosis." (PMID 36828477, 2023). "Coronopilin increases cyclin B1 and p-Cdk1 (Tyr15) levels; however, the upregulation of γH2AX (p-H2AX Ser139) is involved in G1 phase arrest in leukemia (Jurkat and U937) cells." (PMID 35651747, 2022). "In leukemia cells, it was reported that γH2AX (or blockage of H2AX phosphorylation by SB202190) expression sensitizes cells to apoptosis, suggesting a pivotal role of γH2AX in cell death signaling." (PMID 31641425, 2019). "Combination treatments with all studied polyphenols antagonized the formation of γ-H2AX foci induced by methotrexate and 6-mercaptopurine treatments alone, in all the leukemia cell lines (P≤0.05)." (PMID 29285220, 2017). "Primary leukemia blasts isolated from APL patients showed high phosphorylation levels of H2AX (γ-H2AX), an initial DSBs sensor." (PMID 27468685, 2016). "Second, histone deacetylase inhibitors have been found to induce γ-H2AX deposition in several cancer types, especially leukemia." (PMID 20356374, 2010). "Knockout/overexpression of KAT8 correlated positively with phosphorylation of serine 139 in H2A.X variant histone (H2AX), a DNA damage marker (γH2AX), in MLL-AF9 leukemia cells, indicating that KAT8 promotes DNA damage repair and inhibits apoptosis in AF9 cells." (PMID 40508066, 2025). "The leukemia cell line HAP1 was treated with vehicle (DMSO) or 850 nM LP-284 for 6, 24, and 72 hours and stained with phosphorylated H2AX (gH2AX) to monitor HR response and cleaved caspase 3 to monitor apoptosis (n = 2 per group)." (PMID 37306526, 2023). "In three of the Chk1 inhibitor sensitive leukemia/lymphoma cell lines, U937, HL-60 and MV4-11, the endogenous levels of H2AX phosphorylated on Ser139 was much higher compared to all other cell lines." (PMID 24913641, 2014).
cervical carcinoma (18 papers, 2005 to 2025). A carcinoma arising from either the exocervical squamous epithelium or the endocervical glandular epithelium. "In the present study we retrospectively explored the predictive significance of pWee1 and γ-H2AX expression, evaluated in diagnostic biopsies related 52 cervical cancer patients who received neoadjuvant chemotherapy." (PMID 26930412, 2016). "To demonstrate the clinical relevance of our findings, we evaluated the correlation of SETD8, H4K20me1, H4K20me2 and γ-H2AX levels in 62 cervical cancer specimens." (PMID 37308924, 2023). "γ-H2AX and Rad51 foci formation, neutral comet assay and clonogenic cell survival assay were applied to determine the radiosensitivity of cervical cancer cells." (PMID 32907622, 2020). "The percentage of γ-H2AX foci-positive cells was dramatically increased in NEK2-depleted cervical cancer cells after irradiation exposure." (PMID 32907622, 2020). "Here we show that S. aureus can compromise host genomic integrity as indicated by bacteria-induced histone H2AX phosphorylation, a marker of DNA double strand breaks (DSBs), in human cervix cancer HeLa and osteoblast-like MG-63 cells." (PMID 31118484, 2019). "Our results also showed that SKP2 protein increased the ability of clearance of DSBs induced by irradiation in cervical cancer cell lines with decreasing Gamma-H2AX foci number and expression level in SKP2 overexpressing cells after irradiation." (PMID 27317767, 2016). "Association between biomarkers of DNA damage and repair (pWee1 and γ-H2AX) and pathological complete response in cervical cancer patients treated with neoadjuvant chemotherapy (N = 52)." (PMID 26930412, 2016). "To further explore the mechanism by which HCAR1 is involved in the lactate-mediated enhancement of DNA repair and cervical carcinoma cell survival, we studied the kinetics of γ-H2AX foci formation in cells expressing reduced level of HCAR1." (PMID 26208712, 2015). "To determine the intensity of DNA damage response after cisplatin treatment in REV3L overexpression or suppression cervical cancer cell lines, we detected γ-H2AX (pS139) foci formation using immunofluorescence." (PMID 25781640, 2015). "Previous studies have shown that radiation‐induced DNA damage increases γ‐H2AX foci‐positive cells among NEK2‐inhibited cervical cancer cells and reduces the focal positivity of HR regulators involved in DNA repair, confirming that NEK2 knockdown accelerates DNA damage." (PMID 38426218, 2024). "Moreover, immunofluorescence staining of γ-H2AX (Ser139) showed that downregulation of CENPK led to enhanced DNA damage in cervical cancer cells treated with platinum-based drugs." (PMID 35418160, 2022). "However, pre-treatment with the ROS scavenger NAC abrogated the expression of p-H2AX in both the cervical cancer cell lines." (PMID 26621832, 2015). "Although differences in the loss of γ-H2AX foci have been found to be related in part to the intrinsic radiosensitivity of cervical cancer cell lines, our data did not support these observations." (PMID 15785736, 2005). "We hope to further validate the γ-H2AX FDR as a predictive marker within a population of prostate and cervical cancer patients, with the final aim of developing a reliable predictive model to support decision making in radiation therapy practice." (PMID 35406443, 2022). "Normal tissue cells, human SiHa cervical carcinoma cells, and more radiosensitive SCCVII tumor cells tend to have a higher number of γ‐H2AX foci shortly after 10–20 Gy irradiation and show a slower decline in γ‐H2AX foci over time, indicating impairment of DNA repair mechanisms." (PMID 39425547, 2025).
colorectal cancer (18 papers, 2012 to 2026). A primary or metastatic malignant neoplasm that affects the colon or rectum. "High γ-H2AX expression was associated with worse overall survival in colorectal cancer and non-small cell lung cancer." (PMID 38502354, 2024). "Intraperitoneal injection with CS-6 inhibited tumor growth in nude mice with colorectal cancer, and promoted the protein expression of phosphorylated H2A histone family member X (γH2AX), p62, phosphorylated Ataxia-telangiectasia mutated kinase (p-ATM) and LC3 I/II." (PMID 40417224, 2025). "We have shown that loss of γ-H2AX expression has a tendency towards worse survival in colorectal cancer in those patients who have undergone pre-operative radiotherapy, thus suggesting that DSB repair deficient tumours may be non-responders to radiotherapy." (PMID 23154512, 2012). "H2AX has been proposed as a factor to assess response to treatment, and several agents and chemotherapeutic drugs used in colorectal cancer treatment have been shown to increase γ-H2AX, including oxaliplatin, sorafenib, valproic acid, and oncolytic adenovirus." (PMID 32821342, 2020). "Our recent in vivo data revealed a smaller increase in γ-H2AX levels in UC-CRC compared to colorectal cancer (CRC), which led us to propose that colitis-triggered inflammation masked DNA damage as has been shown for C3 cells in vitro." (PMID 28751935, 2017). "Moreover, high γ-H2AX expression was correlated with higher tumor stage and perineural invasion in patients suffering from colorectal cancer." (PMID 38502354, 2024). "In this study, we examined the expression of g-H2AX, ATM and Ku70 in a set of 908 stage II/III colorectal cancers." (PMID 23154512, 2012). "We wished to ascertain the relationship of altered expression of the DSB repair proteins γ-H2AX (gamma-H2AX), ATM and Ku70 with biological and clinico-pathological features of colorectal cancer." (PMID 23154512, 2012). "We have carried out a large-scale investigation of the expression of the double strand break repair proteins γ-H2AX, ATM and Ku70 in colorectal cancer." (PMID 23154512, 2012). "In murine (MC38) and human (HCT116) colorectal cancer cells, CF10 induced significantly higher levels of ICD markers-extracellular ATP, HMGB1 release, and surface calreticulin-than 5-FU and triggered robust Top1cc stabilization with γ-H2AX foci formation." (PMID 42019467, 2026). "No previous studies have examined the role of γ-H2AX in colorectal cancer in this way, and none that have compared DSB repair protein expression with the presence of CIN." (PMID 23154512, 2012).
bladder cancer (16 papers, 2008 to 2025). "Nonetheless, further investigation is needed to determine whether the loss of LEADR in bladder cancer cells can induce replicative stress and DNA damage, for instance, by analysing levels of phosphorylated histone H2AX and key proteins involved in DDR." (PMID 40461454, 2025). "Taken together, these results imply that 19-BJB activates the phosphorylation of DNA damage response-related proteins, such as Chk1, Chk2, and Histone H2AX, influencing the cleavage of caspase-3 and indicating apoptotic effects against bladder cancer cells." (PMID 33724994, 2021). "Subsequently, it was identified as a tumor suppressor through inhibition of cell proliferation by microRNAs in bladder cancer and by interaction with H2AX in lung adenocarcinoma." (PMID 30367150, 2019). "Collectively, these results indicated that in RNF8-silenced bladder cancer cells, γ-H2AX and MDC1, which function upstream of RNF8, clearly formed IRIF after radiotherapy." (PMID 26788910, 2016). "Choudhry and colleagues examined protein expression of MRE11, RAD50, NBS1, ATM, and H2AX by immunohistochemistry in pretreatment tumor specimens from 179 bladder cancer patients receiving radical radiotherapy." (PMID 26198537, 2015). "Enhanced presences of γ-H2AX foci have been found in bladder cancer, human squamous cell carcinoma and NSCLC cancer cells treated with IR in the presence of TKIs, including afatinib." (PMID 25714021, 2015). "γ-H2AX is a biomarker of DNA damage and is useful for predicting urinary bladder cancer." (PMID 38254636, 2023). "On the other hand, it was confirmed that the siFOXM1 group remained, the number of γ-H2AX foci was over the same period of repair in 5637 and KU7 bladder cancer cell lines." (PMID 32486251, 2020). "As MRE11, NBS1, RAD50, ATM, and H2AX interact with each other to facilitate DSB damage signalling, we hypothesized that there may be a gene dosage effect in our study, with subjects with increasing numbers of high risk alleles having an increased risk of bladder cancer." (PMID 18638378, 2008). "Moreover, in a cohort of bladder cancer patients, the expression of YTHDC1 was positively correlated with PTEN and γ‐H2AX levels, and lower YTHDC1 levels were specifically found in chemo‐resistant patients." (PMID 37070134, 2023). "In a panel of 36 sections with bladder cancer, we found a significant positive correlation between levels of YTHDC1 and γ‐H2AX, as illustrated by higher YTHDC1 expressing tumours displayed with higher γ‐H2AX expression." (PMID 37070134, 2023). "In head and neck and bladder cancer cell lines, Fokas and coworkers reported that BEZ235 treatment prolonged ionizing radiation-induced DNA damage, as evidenced by the increased production of γ-H2AX, and enhanced the antivascular effect of RT by attenuating VEGF-associated effects." (PMID 31430901, 2019). "To explore whether RNF8 participated in the DDR in bladder cancer cells, we utilized T24 cells to examine the process of post-irradiation DNA damage repair in the presence or absence of RNF8 knockdown by detecting γ-H2AX foci at different time points." (PMID 26788910, 2016).